ENG (endoglin)
Diseases named in the same sentence as ENG in open-access papers (continued):
Sharing a sentence is not in itself a finding about the gene and the disease.
vascular malformation (18 papers, 2008 to 2025). A non-neoplastic disorder that is the result of defects of vascular morphogenesis. "HHT is a rare genetic disease leading to vascular malformations, caused by pathogenic variants in ENG or ACVRL1, the two major genes." (PMID 36059817, 2022). "The endoglin levels were low in skin, lung, intestine and brain, organs described as being susceptible to the development of vascular malformations in patients with HHT1, compared to heart, kidney and liver." (PMID 34445652, 2021). "In humans, hereditary haemorrhagic telangiectasia type 1 (HHT1), which is characterized by vascular malformations, is attributed to the mutation of the ENG gene." (PMID 29484142, 2018). "In addition to Endoglin, some other TGFβ signaling pathway components have been implicated in several single gene disorders involving vascular malformations." (PMID 35281255, 2022). "Moreover, Activin receptor-like kinase-1/ALK1 (Acvrl1) is downregulated ×1.8 fold, and both Acvrl1 and Endoglin mutations are associated with Hereditary Haemorrhagic Telangiectasia diseases, characterized by bleeding from vascular malformations." (PMID 26090377, 2014). "Coherent with this notion, NOS3, the enzyme required for constitutive NO formation in ECs has been shown to be downregulated in ECs harvested from HHT patients, a pathology due to heterozygous mutations in either endoglin or Alk1 and characterized by multiple vascular malformations." (PMID 19340291, 2009). "The biallelic loss of ENG in this case would lead to a loss of protein expression, and we hypothesize that a loss of heterozygosity in endothelial cells is a central mechanism, leading to vascular malformations in HHT." (PMID 39062925, 2024). "When ENG was identified as the first HHT gene, the two-hit mutation mechanism was proposed as a potential molecular mechanism for vascular malformations associated with HHT." (PMID 40648852, 2025). "Endoglin knockdown in ECs results in a clear AVM phenotype in the neonatal retinal vasculature that is reminiscent of vascular malformations in HHT." (PMID 25741358, 2015). "In this way, somatic mutations would increase the number of ECs that are null for endoglin (in HHT1) or null for ACVRL1 (in HHT2) and following exposure to angiogenic or inflammatory signals these “null” ECs would be associated with vascular malformations." (PMID 25741358, 2015). "Transgenic mice deficient in TGF-β-1, TGF-β receptor 1 (ALK1), TGF-β receptor 2 (ALK4), or the accessory TGF-β-binding protein endoglin, suffer from defects in angiogenesis and vascular malformations." (PMID 18334936, 2008). "First, we performed manual analysis and variant calling of the sequencing data for the genes known to cause HHT (ACVRL1, ENG, GDF2, SMAD4) or vascular malformation syndromes with similar phenotypes (EPHB4, RASA1), as well as PIK3CA, which has been shown to modify vascular malformation phenotypes." (PMID 39062925, 2024). "ENG and ALK1 are cell-surface transmembrane receptors involved in TGF-β1 and BMP signaling pathways that can activate pSMAD1/5/8, and impairment or mutations of ENG and or ALK1 signaling can lead to vascular malformations associated with HHT disease." (PMID 35380991, 2022). "For example, the ACVRL1c.314-35A>G common variant was shown to be associated with sporadic brain AVMs, and also subsequently with PAVMs as well as vascular malformations overall in patients with ENG mutations, but not in patients with ACVRL1 mutations." (PMID 33167572, 2020). "These two HHT1 brain AVM models show that VEGF induces AVMs in the Eng heterozygous adult mouse brain, suggesting that VEGF stimulation may play a pivotal role in the initiation and development of vascular malformations in states of endoglin insufficiency present in HHT1 patients." (PMID 33167572, 2020). "The lack of Endoglin results in impaired neoangiogenesis and vascular malformations because of the alterations of endothelial cell physiology." (PMID 36594057, 2023).
vascular malformation (continued). "However, the role of TGF-β1/ALK1 or TGF-β1/ENG signaling in vascular SMCs in vascular remodeling and vascular malformations has not been defined." (PMID 35380991, 2022). "Genetic analyses of ACVRL1, ENG, and SMAD4 (in addition to EPHB4 and RASA1) are considered reasonable in all cases of high-flow intracerebral vascular malformations regardless of other HHT signs." (PMID 40259928, 2025).
liver fibrosis (17 papers, 2013 to 2025). "Further studies are needed to fully understand the role of the BMP9–endoglin axis in liver fibrosis and its underlying mechanisms." (PMID 39199400, 2024). "An additional SNP was found in a regulatory region of the endoglin gene in relation to increased risk of liver fibrosis in HCV patients and predicted to decrease the DNA-binding affinity of HNF4α (involved in the expression of liver-specific genes)." (PMID 34065048, 2021). "Recently, a novel variant with a low-frequency missense variant (Thr5Met) in the ENG gene, encoding endoglin, was associated with liver fibrosis development in HCV patients." (PMID 33809908, 2021). "In an attempt to discover novel determinants of HCV-related liver fibrosis progression, a joint French/Swiss study group identified an endoglin variant, Thr5Met, the frequency of which was higher among HCV/fibrosis patients than among HCV/controls." (PMID 34065048, 2021). "In a murine model for liver fibrosis, endoglin deficiency enhanced the expression of pro-fibrotic factors such as α-SMA and fibronectin." (PMID 32059544, 2020). "We identified one low frequency missense variant (Thr5Met) in ENG gene, encoding endoglin, associated with liver fibrosis development." (PMID 31749832, 2019). "Endoglin expression is also enhanced during experimental liver fibrosis, and serum endoglin levels have been associated with hepatic fibrogenesis." (PMID 24670474, 2014). "Previous experiments demonstrate that during liver fibrosis induced by different causes, the circulating endoglin level is significantly increased." (PMID 25393508, 2014). "In a more relevant murine model of liver fibrosis, endoglin deficiency in HSC was recently shown to significantly aggravate liver fibrosis in response to injury suggesting a protective role of endoglin against liver fibrosis." (PMID 31749832, 2019). "The upregulation of endoglin has been commonly observed in liver injuries, suggesting its potential as a serum biomarker for liver fibrosis." (PMID 39199400, 2024). "Endoglin expression was found to be increased in transdifferentiating hepatic stellate cells (HSCs) in a liver fibrosis model." (PMID 33809908, 2021). "In liver fibrosis, HSCs upregulate endoglin during trans differentiation, both in vitro and in rat models for liver fibrosis." (PMID 32059544, 2020). "Both increased circulating and hepatic tissue levels of Endoglin appear to correlate with increased liver fibrosis stage." (PMID 32454407, 2020). "Several reviews highlight the role of endoglin in liver fibrosis, myocardial fibrosis, and kidney fibrosis." (PMID 32059544, 2020). "Although in other systems both pro- and antifibrotic actions for endoglin have been described, in hepatic fibrosis accumulating evidence points towards a profibrotic role for this protein." (PMID 29295498, 2017). "A recent study has shown that Endoglin expression is increased in transdifferentiating hepatic stellate cells in vitro and in models of liver fibrosis in vivo." (PMID 23516586, 2013). "However, the co-receptor endoglin exerts a protective effect against liver fibrosis through the ALK5–Smad2/3 signaling pathway." (PMID 39199400, 2024). "Soluble endoglin (sEng) levels are reported to be elevated in liver fibrosis." (PMID 32454407, 2020). "In addition to endoglin expression on stellate cells, several studies have also shown increased levels of sol-eng in circulation during liver fibrosis." (PMID 32059544, 2020). "In addition, TRC205 (also developed by Tracon Pharmaceuticals), an IgG4 antibody against human endoglin, is currently being tested in preclinical studies for its ability to reduce liver fibrosis." (PMID 33081058, 2020). "TRC105, a monoclonal antibody that binds endoglin, is being analysed in more than 20 clinical trials as an anti-angiogenic drug in different tumour types but once again, a deeper knowledge on the exact function of endoglin in liver fibrosis is needed before taking a step forward." (PMID 29295498, 2017).
liver fibrosis (continued). "Furthermore, endoglin expression increases in HSC in two different models of liver fibrosis (bile duct ligation and CCl4 administration); and in HSC undergoing transdifferentiation in vitro." (PMID 29295498, 2017). "Given that the BMP9 receptors ALK1 and Endoglin, as well as the BMP9 downstream targets Hepcidin and ID1, have significant roles in liver fibrosis, we will comprehensively discuss each of these components individually." (PMID 39199400, 2024). "In conclusion, endoglin plays a role in fibrogenic Smad signaling and regulates TGF-β and BMP signals in liver fibrosis by modulating the ALK5–Smad2/3 pathway and enhancing the ALK1–Smad1/5 pathway." (PMID 39199400, 2024). "Thus, endoglin may contribute to liver fibrosis in chronic HCV-infected patients." (PMID 33809908, 2021). "In line with this, it has been shown in several studies that endoglin can enhance TGF-β1-induced Smad1/5 and/or Smad2/3 phosphorylation in scleroderma fibroblasts, liver fibrosis, and cardiac fibrosis." (PMID 33081058, 2020). "Since both endoglin and BMP7 are expressed in HSC, it would be interesting to know if a similar effect is accomplished in this population during liver fibrosis." (PMID 29295498, 2017). "Endoglin exerts a remarkable regulatory effect on BMP signaling by regulating Smad phosphorylation; it plays an important role in liver fibrosis." (PMID 25393508, 2014). "This review summarizes the indirect connection between BMP9 and liver fibrosis, with a focus on the BMP9 signaling pathway members ALK1, endoglin, Id1, hepcidin and Snail." (PMID 25393508, 2014). "Since several studies have investigated the role of endoglin and its ligand BMP-9 in the progression of liver fibrosis, this might be an interesting field of study." (PMID 33375670, 2020). "Taken together, these results suggest that increased expression of TIMP-4 and Endoglin represents a mechanism specific for hepatic fibrosis that correlates with hepatic staging but is irrespective of the underlying etiology of liver disease." (PMID 23516586, 2013).
myocardial infarction (17 papers, 2010 to 2025). Gross necrosis of the myocardium, as a result of interruption of the blood supply to the area, as in coronary thrombosis. "In other words, the predominant HHT genotypes (ACVRL1+/− and ENG+/−) both represent an ALK-1-deficient state in which reduced rates of myocardial infarction were reported by patients in an unbiased survey." (PMID 38202257, 2023). "After inducing myocardial infarction (MI), wild type (WT) and endoglin heterozygous (Eng+/-) mice were treated for 5 days with the DPP4 inhibitor Diprotin A (DipA)." (PMID 29253907, 2017). "This miRNA was reported to increase endoglin expression to induce myocardial fibrosis with acute myocardial infarction (AMI)." (PMID 26754670, 2016). "Also, changes of Sol-endoglin plasma levels after an acute myocardial infarct are accurate predictors of acute mortality in these patients." (PMID 21171985, 2010). "In this study, we showed that monocytes depend on the expression of endoglin to be able to differentiate from an inflammatory M1 macrophage towards a reparative M2 macrophage and that endoglin heterozygosity prolongs the inflammatory response after myocardial infarction." (PMID 33670533, 2021). "Endoglin is an MSC marker and it is expressed in progenitor cells involved in vascular remodelling in animal models of myocardial infarction and rheumatic diseases." (PMID 33235244, 2020). "64Cu-NOTA-TRC105-(Fab) has been employed in three different cardiovascular disease models to achieve endoglin-based PET imaging: murine hindlimb ischemia, rat myocardial infarction (MI), mouse calcium-phosphate-induced AAA." (PMID 33946583, 2021).
metastatic disease (16 papers, 2003 to 2023). "Our studies demonstrate that loss of BMPRII precludes endoglin from suppressing invasion, which in humans would be predicted to translate into poorer survival due to the increased development of metastatic disease." (PMID 23967299, 2013).
breast tumor (14 papers, 2007 to 2025). "For instance, brain and heart-metastatic breast-tumour cells also express endoglin in large amounts." (PMID 23343205, 2013). "In addition, ENG gene methylation was associated with the lack of ENG in human breast tumors and a poor clinical outcome." (PMID 33804796, 2021). "The earliest studies on endoglin-based imaging with the use of nanomaterials described the application of 64Cu and 66Ga radiolabeled, ultra-high surface area TRC-105-nanographene as potent in vivo imaging tracer for the 4T1 breast tumor vasculature." (PMID 33946583, 2021).
heart failure (13 papers, 2013 to 2026). Inability of the heart to pump blood at an adequate rate to meet tissue metabolic requirements. "Endoglin-deficient zebrafish develop cardiomegaly, resulting in heart failure and hypochromic anemia, which both stem from chronic hypoxia." (PMID 37264878, 2023). "Overall, our data link Endoglin deficiency to heart failure and establish zebrafish as a valuable HHT model." (PMID 37264878, 2023). "Altogether, these results showed that hypoxia-induced erythropoiesis is a major contributor to heart failure in Endoglin-deficient zebrafish." (PMID 37264878, 2023). "The underlying mechanisms precipitating myocardial fibrosis and heart failure are therefore different and the importance of endoglin in these different pathologies probably varies." (PMID 23894375, 2013). "Interestingly though, ALK1, BMP9/BMP10 and endoglin knockout in adult mice similarly result in high-output heart failure, as does Bmp10 deficiency in zebrafish." (PMID 37264878, 2023). "We showed that the health and survival of Endoglin-deficient fish can be strongly enhanced by treatment with the hemolytic agent phz, demonstrating that increased hematocrit/blood viscosity induced by hypoxia is a main driver of heart failure in these fish." (PMID 37264878, 2023). "Finally, phenylhydrazine treatment demonstrated that lowering hematocrit/blood viscosity alleviates heart failure and enhances the survival of Endoglin-deficient fish." (PMID 37264878, 2023). "Finally, we found that, individually re-expressed in Endoglin-deficient fish, the phylogenetically conserved Endoglin long and short isoforms similarly rescue heart failure." (PMID 37264878, 2023). "Because phz induces hypoxia via its hemolytic activity, whereas, in endoglin mutant zebrafish, hematocrit/blood viscosity is increased as a result of hypoxia, we assessed whether increased hematocrit would contribute to heart failure in Endoglin-deficient fish." (PMID 37264878, 2023). "In human subjects with heart failure, endoglin expression is increased in cardiac fibroblasts of the failing left ventricle." (PMID 36614087, 2022). "For instance, it has been described that endoglin is upregulated in cardiac fibroblasts in the left ventricle of patients with heart failure." (PMID 36614087, 2022). "Angiotensin II (Ang II) has been found to induce the endoglin expression in cultured cardiac fibroblasts (CFs), and also found in mice 6, 7 and patient 8 with heart failure." (PMID 27306149, 2016). "We demonstrated that EGCG attenuated myocardial fibrosis and heart failure by the suppressing endoglin and the JNK/AP‐1 pathway, and the anti‐inflammatory results suggested that it had the strong implications in controlling human cardiovascular diseases." (PMID 27306149, 2016). "Reduced ENG activity led to attenuated cardiac fibrosis and increased survival in an in vivo model of heart failure." (PMID 28509980, 2015). "We sought to investigate the mechanism of regulation of mir-208a and endoglin in volume overload-induced heart failure." (PMID 24392114, 2014). "Endoglin has been used as a noninvasive measure of left ventricular filling pressure in heart failure and has been regarded as a new biomarker for acute heart failure." (PMID 24392114, 2014). "In conclusion, we demonstrate for the first time that mir-208a increases endoglin expression to induce myocardial fibrosis in volume overloaded heart failure." (PMID 24392114, 2014). "Endoglin expression is increased in human hearts with severe left ventricular failure and in heart failure induced by transaortic constriction, a pressure overload in mice." (PMID 24392114, 2014). "In conclusion, mir-208a increased endoglin expression to induce myocardial fibrosis in volume overloaded heart failure." (PMID 24392114, 2014). "Enhanced survival clearly demonstrates that this prevents heart failure in endoglin mutants." (PMID 37264878, 2023).
heart failure (continued). "Altogether, these data showed that Endoglin deficiency does not impact early heart development but instead results in cardiomegaly at later stages, leading eventually to terminal heart failure." (PMID 37264878, 2023). "Endoglin expression is increased in patients with heart failure." (PMID 24392114, 2014). "Therefore, targeted endoglin therapy for preventing myocardial fibrosis and heart failure may improve the clinical outcome in patients with heart failure." (PMID 27306149, 2016). "It has been reported that miR-208a promotes heart failure progress through modulating cardiac fibrosis through increasing endoglin and collagen I expression and hypertrophy, and could be a biomarker for diagnosis and therapeutic target in treatment of heart failure." (PMID 27504893, 2016). "Colocalisation with heart failure implicates 23 shared loci and bioinformatic analysis prioritises genes including HSPB7, CAMK2D, ALDH2, ENG, and YWHAE." (PMID 41760662, 2026). "Therefore, targeting endoglin to prevent fibrosis and heart failure may improve clinical outcome in patients with heart failure in addition to the current clinical benefits of β-adrenergic receptor antagonists, angiotensin-converting enzyme or receptor blockers and aldosterone antagonists." (PMID 24392114, 2014). "Supporting the notion of endoglin as a pro-fibrotic molecule, the reduced endoglin levels in heterozygous endoglin-knockout (ENG+/-) mice reduce cardiac fibrosis in a model of pressure overload-induced heart failure." (PMID 33081058, 2020). "In order to define whether heart failure in eng−/− fish relies on the lack of a specific Endoglin isoform, we produced transgenic lines expressing either long or short isoform Endoglin under the regulation of the EC-specific zebrafish fli1a promoter/enhancer." (PMID 37264878, 2023). "Notably, endoglin expression was absent in the heart at these stages, indicating that heart failure in eng−/− zebrafish is indirect." (PMID 37264878, 2023).
osteosarcoma (13 papers, 2010 to 2026). A usually aggressive malignant bone-forming mesenchymal neoplasm, predominantly affecting adolescents and young adults. "Peptide nABP296 was identified as having the highest affinity for the endoglin-expressing MNNG/HOS cell line (human osteosarcoma) and was conjugated with the fluorescent dye fluorescein-5-isothiocyanate (FITC)." (PMID 33946583, 2021).
colon carcinoma (12 papers, 2007 to 2022). "Although Pauuwe and colleagues reported the expression of endoglin by TAFs in colon carcinoma, we could not see this in our tumor models from mEnd-IL injected mice." (PMID 32316521, 2020).